LDHB (lactate dehydrogenase B)
Diseases named in the same sentence as LDHB in open-access papers (continued):
Sharing a sentence is not in itself a finding about the gene and the disease.
cancer (continued). "LDHB, PTPRS, UHRF1, and TUBB3 were proposed as universal prognostic and malignancy markers across many cancer types." (PMID 36900348, 2023). "In line with this, SIRT5 KO or LDHB KD reduced CRC cell growth, and cancer cells overexpressing wild-type LDHB expanded more quickly than those overexpressing LDHB-K329Q." (PMID 36980194, 2023). "In fact, previous studies have highlighted the dispensability of the Warburg effect in cancer cell growth and have shown that a complete disruption of glycolysis would require the deletion of both LDHA and LDHB genes." (PMID 36768924, 2023). "These include: CDH1, MUC1, THBS4, and MSLN for PEs related to cancer; ADA2, CXCL10, and WARS for TB-PEs; CRP, S100A9, and VIM for parapneumonic PEs; and C9, LDHA, HPX, LDHB, and C3 for benign-PEs." (PMID 35197508, 2022). "Similarly, LDHB expression may be used as a biomarker for therapy response in various cancers." (PMID 35646923, 2022). "LDHA and LDHB are highly expressed in cancers, with LDHA responsible for converting pyruvate to lactate and LDHB responsible for converting lactate to pyruvate." (PMID 36230492, 2022). "In the non-irradiated cell experiments, the expression levels of LDHA and LDHB were highest in the HMC3 microglial cells, followed by the FaDu cancer cells, then they relatively lower in the THP-1 monocytes." (PMID 34436459, 2021). "The irradiated FaDu cancer cells showed significantly decreased expression levels of LDHA and LDHB (p = 0.049 and 0.001, respectively)." (PMID 34436459, 2021). "Four LDH genes are known in the vertebrates, i.e., LDHA, LDHB, LDHC, and LDHD, which are critically involved in cancer metabolism." (PMID 34822416, 2021). "Several studies have reported that LDHB is constitutively expressed in various cancer cell types, while LDHA is proposedly important for tumor initiation as it is often overexpressed in cancer." (PMID 33199724, 2020). "We show that higher lactate concentration in cancer tissue is concomitant with a shift in isozyme pattern towards the “muscle-type” LDH and corresponding LDHA and LDHB protein expression changes." (PMID 33353120, 2020). "The finding that the deacetylation of LDHB by SIRT5 promotes autophagy and cancer cell proliferation led us to examine K329 acetylation status in human CRC tissues." (PMID 30443978, 2019). "Lactate dehydrogenase B, catalysing the conversion of lactate and NAD+ to pyruvate, NADH and H+, is a key contributor to lysosomal acidification and autophagy in cancer." (PMID 30443978, 2019). "Together, these results demonstrated that Aurora-A-mediated LDHB S162 phosphorylation promotes NAD+ regeneration, glycolytic flux, lactate production and biosynthesis with glycolytic metabolites in cancer cells." (PMID 31804482, 2019). "Thus, the promotion of autophagy by SIRT5 via LDHB suggested that they might affect cancer growth." (PMID 30443978, 2019). "LDHB transcription is also directly stimulated by the signal transducer and activator of transcription 3 (STAT3), a key tumorigenic driver in many cancers." (PMID 31035592, 2019). "LDHB was found to be positively regulated by the RTK–PI3K–AKT–mTOR pathway both in immortalized mouse cell lines and human cancer cells." (PMID 29326883, 2017). "This is in line with the “reverse Warburg effect,” proposing that stromal or cancer cells undergo aerobic glycolysis and produce lactate, which is then taken up by MCT1 to fuel oxidative cells via LDHB-catalyzed conversion to pyruvate." (PMID 29326883, 2017). "Expression of mammalian LDHA and LDHB is regulated during development and is tissue specific; therefore, alterations in the LDH levels serve as indicators of pathologic involvement and cancer development." (PMID 25372838, 2014). "Five enzymes (LDHB, MDH2, PKM2, AKR1B1, and AKR1B10) out of 40 enzymes in pyruvate metabolism pathway are overexpressed in cancer." (PMID 25243088, 2014).
cancer (continued). "LDHB, when present, is constitutively expressed, whereas LDHA is inducible in hypoxic conditions and often overexpressed in cancers with a MYC amplification." (PMID 24280423, 2013). "Notably, we previously showed that top genes of this program (LDHB, GSTK1, DGKA, APRT, MGAT4A, and NMRK1) are predictive of the response of patients with cancer to ICIs." (PMID 40187353, 2025). "Specifically, LDHB was shown to be positively regulated by the RTK–PI3K–AKT–mTOR signaling axis and stimulated by signal transducer and activator of transcription 3 (STAT3), a key tumorigenic driver across numerous cancers." (PMID 40733189, 2025). "Although typically suppressed or absent from cancers such as pancreatic, gastric, prostate, and hepatocellular carcinomas, LDHB expression is paradoxically upregulated in specific aggressive cancer subtypes." (PMID 40733189, 2025). "While cancer cells overexpress lactate dehydrogenase A (LDHA) to support glycolytic flux and lactate production, the role of LDHB-which preferentially catalyzes lactate oxidation-remains unclear." (PMID 40940446, 2025). "Given LDHB’s emerging role in cancer metabolism, particularly in tissues with high oxidative demands or in tumors that switch from LDHA to LDHB expression, selective LDHB inhibition may provide unique therapeutic advantages." (PMID 40733189, 2025). "In this situation, lactate dehydrogenase B (LDHB), catalyzing the conversion of lactate and NAD+ to pyruvate, NADH and H+, controls vesicle maturation, lysosomal acidification, and intracellular proteolysis in cancer cells." (PMID 39010155, 2024). "Cancer cells use monocarboxylate transporter protein 1 (MCT1) to uptake lactate and convert it to pyruvate via the enzymatic activity of lactate dehydrogenase-B (LDH-B)." (PMID 38965505, 2024). "As with Akt inhibition, LDHB inhibition was found to be useful in cancer therapy, but selective LDHB inhibitors have not been discovered as of yet." (PMID 36891273, 2023). "Except for LDHA and LDHB, LDHC and LDHD are expressed in various cancers." (PMID 37547725, 2023). "Furthermore, a recent study reported that lactate dehydrogenase B (LDHB) controls lysosome activity and autophagy in cancer." (PMID 36980995, 2023). "In addition to being a crucial autophagy regulator, LDHB converts lactate to pyruvate, which powers the TCA cycle and helps oxidative cancer cells." (PMID 36980194, 2023). "Except for LDHA and LDHB, LDHD also has been described in some cancers." (PMID 36612084, 2022). "Together, these results suggest an essential role for LDHB in NSCLC tumorigenesis and growth that may be cancer-specific." (PMID 35877003, 2022). "In 2016, a research team cataloged GNE-140 from a high throughput screening of two million compounds as having ability to inhibit LDHA, LDHB, and LDHC with IC50s in the nanomolar range, which could entirely block lactic acid production in cancer cells." (PMID 34944395, 2021). "We observed a shift from the LDHB isoform to the LDHA isoform, which is typical of cancer cells." (PMID 34205977, 2021). "In contrast, another study reported that LDHB and MCT-1 are also involved in cancer metabolism." (PMID 31936895, 2020). "Based on the observations of LDHA- and LDHB-mediated cancer progression, we can speculate that LDHC could be involved in metabolic reprograming of cancer cells." (PMID 31932876, 2020). "SIRT5-induced LDHB deacetylation hyperactivates autophagy and targeting SIRT5/LDHB pathway could be highly useful in LDHB positive cancers." (PMID 31146503, 2019). "Taken together, these data demonstrate that LDHB, but not LDHA, controls the basal autophagic flux of oxidative cancer cells, and silencing LDHB inhibits basal autophagy, cancer cell proliferation, and also leads to apoptosis." (PMID 31035592, 2019). "Cancer cells then uptake the lactate using monocarboxylate transporter 1 (MCT1) and convert it to pyruvate by the enzymatic activity of lactate dehydrogenase-B (LDH-B)." (PMID 30634433, 2019).
cancer (continued). "Besides being an important regulator in autophagy, LDHB oxidates lactate to pyruvate, which fuels the TCA cycle and benefits for oxidative cancer cells." (PMID 30443978, 2019). "Protons (H+) generated by LDHB promote lysosomal acidification and autophagy in cancer, but how this role is regulated has not been defined." (PMID 30443978, 2019). "Some data, as knocking down LDHB, showed no apparent effect (similarly to LDHA) on apoptosis induction in cancer cells and silencing of the LDHB gene does not increase the cellular NADH/NAD+ ratio in these cells." (PMID 31035592, 2019). "LDHB is a key enzyme that catalyzes the conversion of lactate to pyruvate and NAD+ to NADH (an oxidized and reduced form of nicotinamide adenine dinucleotide, respectively) and is known to play important roles in cancer cell growth and progression." (PMID 30441870, 2018). "LDHB activity is necessary for cancer cell proliferation not only in oxidative cancer cells, but also in glycolytic cancer cells." (PMID 28937628, 2017). "Another intriguing finding is that LDHB specifically affected sensitivity of cancer cells to taxol but not to either cisplatin or 5-fluorouracil." (PMID 25973606, 2015). "However, to the best of our knowledge, there are no studies on how silencing LDHB affects the response of cancer cells to radiotherapy." (PMID 40158058, 2025). "Thus, our experiments revealed that silencing LDHB, but not LDHA, augments RSL3-induced loss of viability in cancer cells." (PMID 40090955, 2025). "In addition, our in silico analysis of the 1739 cancer cell lines and 10967 cancer patient samples revealed a significant negative correlation between LDHB and GPX4 expression, i.e., either one of the two genes is highly expressed but rarely both together." (PMID 40090955, 2025). "However, the specific mechanism through which LDHA and LDHB regulate cancer metabolism has not been fully elucidated, and their impact on PCa glycolysis requires further research." (PMID 38764020, 2024). "Scientists have discovered that LDHB is consistently expressed in different types of cancer cells, whereas LDHA may play an important role in tumor initiation since it is frequently overexpressed in cancer." (PMID 37415191, 2023). "Considering the importance of LDH in cancer metabolism and HO-1-mediated effects on this enzyme transcription and activity in PCa cells, we searched public database repositories and performed a bioinformatics analysis to determine the clinical significance of LDHA, LDHB and HMOX1." (PMID 34208670, 2021). "Consistent with previous findings in other types of human cancer, reduced LDHB and hnRNPF expressions were observedboth at the mRNA and protein levels in MCC-2 and MCC-3 cells following mTOR pathway inhibition, indicating that LDHB and hnRNPF are downstream effectors of mTOR pathway." (PMID 25284964, 2013). "The Cancer-Induced Lactate Load and Oncologic Remodeling (CILLO) hypothesis proposes that lactate, either imported through MCT1 or produced endogenously, is oxidized to pyruvate by LDHB and subsequently carboxylated to oxaloacetate (OAA) by pyruvate carboxylase." (PMID 41142618, 2025). "Interestingly, LDHB and HK2 are localized to the inner and outer mitochondrial membrane, respectively, and there may be a link between their expression and mitochondrial apoptosis in cancer cells." (PMID 33849427, 2021). "The experiments with targeting LDHA and LDHB showed that LDHB, but not LDHA, controls lysosomal activity and basal autophagic flux of cancer cells." (PMID 31035592, 2019). "Here, we demonstrate that LDHB, but not LDHA, is essential for mitotic progression in cancers." (PMID 40940446, 2025).
infection (11 papers, 2019 to 2025). The state of being infected such as from the introduction of a foreign agent such as serum, vaccine, antigenic substance or organism. "We reveal significant reductions in metabolism in pDCs, show that the metabolic enzyme lactate dehydrogenase B (LDHB) is downregulated in mouse and human pDCs exhibiting infection-driven loss of function, and find that LDHB supports IFN-I production in pDCs in vitro and in vivo." (PMID 39920132, 2025). "We chose mouse hepatitis virus (MHV) as a model system to investigate the importance of LDHB in pDCs during an in vivo infection." (PMID 39920132, 2025). "Altogether, our results identify a key role for LDHB in balancing pDC antiviral function and immunopathogenic potential during infection." (PMID 39920132, 2025). "Furthermore, restoring LDHB in vivo in pDCs from infected mice increases IFNAR-dependent, infection-associated pathology." (PMID 39920132, 2025). "Mechanistically, we identify lactate dehydrogenase B (LDHB) as a positive regulator of pDC IFN-I production in mice and humans; meanwhile, LDHB deficiency is associated with suppressed IFN-I production, pDC metabolic capacity, and viral control following infection." (PMID 39920132, 2025). "While various environmental factors may contribute to the observed pDC metabolic alterations, in this study we focused on LDHB downregulation, a shared phenotype across different anatomical compartments, time points post-infection, viruses, and species." (PMID 39920132, 2025). "To determine if LDHB in pDCs contributed to their capacity for IFN-I production during infection, and promoted anti-viral responses, we made mixed BM chimeras using a 50:50 ratio of BDCA2-DTR transgenic and LDHB−/− or WT BM respectively." (PMID 39920132, 2025). "Along with our data indicating that LDHB deficiency does not completely ablate pDC IFN-I production or change TNFα production capacity these data reinforce the idea that multiple mechanisms are likely at play in the enforcement of pDC loss of function after infection." (PMID 39920132, 2025). "The contributions of peak infection intensity (titer, TPM, NCAP) and epithelial damage (LDHB) to a pathway-based index of failed epithelial repair (referred to as the repair index) were tested." (PMID 40791384, 2025). "This small increase is, however, difficult to disentangle from the higher viral titers observed in pDC-LDHB−/− mice, but generally supports that LDHB is not necessary for pDCs expression of antigen presentation molecules after infection." (PMID 39920132, 2025). "Furthermore, gene expression of glycolytic enzymes, lactate, and glutamine metabolism (G6PDH, PKLR, PFKL, LDHA, LDHB, GLS1, GLS2, and GLUL), were upregulated in primary mouse (hACE2) and human hepatocytes upon infection compared to controls." (PMID 35978143, 2022). "In ovaries, the higher abundance of uric acid after the infection was correlated with the downregulation of two E. sea bass metabolic genes: Purine nucleoside phosphorylase 5a (pnp5a, PNP human ortholog, log2FC: − 1.96) and lactate dehydrogenase b (ldhb, LDHB human ortholog, log2FC: − 1.35)." (PMID 41241706, 2025). "After 48 h of infection, the fluorescence intensity and proportion of 3D4/21 cells transfected with pEGFP-Cl-LDHB were reduced compared with those transfected with the pEGFP-Cl (blank control) vector, indicating that ASFV replication was decreased when LDHB was overexpressed." (PMID 37508430, 2023). "Amongst genes regulated by infection with acidosis but not at pH 7.4 the Reactome gene set “glycolysis” was enriched and expression of glycolysis genes (HK2, ALDOC, LDHB) was increased by acidosis." (PMID 37418488, 2023).
bacterial infection (1 paper, 2022). "In summary, pathogenic bacterial infection upregulated PKM, LDHB, LDHA, ALDOA, PGD, GPI, and ALDOC, increased ATP production, which promotes leukocyte recruitment and NALP3-inflammasome activation, increases NADPH production, and promotes ROIs modulating inflammation and injury." (PMID 36335251, 2022).
LDHB also shares sentences with these, for which no sentence is quoted: adenocarcinoma (3 papers); colon adenocarcinoma (3); testicular germ cell tumor (3); autism (2); benign tumor (2); cervical cancer (2); colorectal adenocarcinoma (2); diabetes (2); head and neck squamous cell carcinoma (2); Multiple Myeloma (2); pancreatic adenocarcinoma (2); schizophrenia (2); Type 1 diabetes (2); age (1); bladder transitional cell carcinoma (1); brain tumor (1); Cerebral ischemia (1); chronic kidney disease (1); clear cell renal cell carcinoma (1); colorectal (1); Cryptosporidium infection (1); dengue (1); ductal carcinoma in situ (1); dystrophin deficiency (1); esophageal squamous cell carcinoma (1); fibrosarcoma (1); glycogen storage disease (1); herpesvirus infections (1); hypertrophy (1); Hypoglycemia (1).
A further 16 diseases each share a sentence with LDHB in 1 paper.